CEP55 (centrosomal protein 55)
Diseases named in the same sentence as CEP55 in open-access papers (continued):
Sharing a sentence is not in itself a finding about the gene and the disease.
cancer (continued). "Of note, 6 CTA genes CEP55, KIF2C, TTK, OIP5, CASC5, and NUF2 had higher expression levels in the higher-TMB subtype of at least 15 cancer types, while had higher expression levels in the lower-TMB subtype of at most 3 cancer types." (PMID 30634925, 2019). "During characterisation of exosomal proteins, we accidentally identified a potential unique cancer exosomal membrane protein, CEP55, which were present in all 5 cancer exosomes and absent in all 3 normal exosomes." (PMID 30008265, 2018). "The presence of CEP55 on cancer exosomes but not normal exosomes led us to suggest the involvement of different endosome biosynthetic pathways." (PMID 30008265, 2018). "We found that CEP55 is a downstream effector of MAPK signaling through MYC oncogene, which has a central role in transformation, tumorigenesis, and genomic instability, and MYC is deregulated in many cancers." (PMID 30108112, 2018). "Further analysis using immune-gold TEM confirmed that CEP55 protein was located on the membrane of cancer-derived but not normal exosomes." (PMID 30008265, 2018). "In order to determine whether CEP55 induces epithelial–mesenchymal transition (EMT), we probed the cancer cell lines with epithelial and mesenchymal markers." (PMID 26615423, 2016). "However, research on the involvement of CEP55 in pan-cancer is lacking, and the clinical significance and potential mechanisms of this gene in multiple cancers require further elucidation." (PMID 37173675, 2023). "While it has been proven that CEP55 performs a significant function in the progression of several forms of cancer, there has been a lack of investigations analyzing the collective aspects of CEP55 in a panel of human cancers, and because of that, we performed this comprehensive pan-cancer analysis." (PMID 37175004, 2023). "In addition, CEP55 binds and stabilizes the PI3K catalytic subunit and facilitates the activation of the PI3K/Akt pathway, thus promoting the survival and proliferation of cancer cells." (PMID 37484531, 2023). "However, this increase is not in par with cancer cell lines expressing high endogenous CEP55 levels." (PMID 30108112, 2018). "However, the biological function of CEP55 in supporting cancer cell spreading in HCC cancer has not been determined." (PMID 30096813, 2018). "Though several lines of evidence suggest that CEP55 could be a candidate target for therapeutic development, there is currently no specific way to target CEP55 overexpressing cancers." (PMID 30108112, 2018). "Additionally, near‐normal MCF10A and D492 lines exhibited non‐responsive effect following combination treatment, consistent with the idea that CEP55 activity is important in certain cancers but not in normal cells." (PMID 30108112, 2018). "CKS2 (chr9q22.2), CEP55(chr10q23.33), UHRF1 (chr19p13.3), RRM2 (chr2p25.1), AURKA (chr20q13.2), FLJ39632 (chr14q11.2), FAM83D (chr20q11.23), NEK2 (chr1q32.3) and MAD2L (chr4q27) were all located on PCSRs and showed over-expression in the 9, 8, 10, 9, 8, 9, 9, 8 and 9 types of cancers, respectively." (PMID 24796549, 2014). "However, no previous investigation has explored CEP55 expression in pan-cancer." (PMID 37173675, 2023). "Interestingly, CEP55 expression was positively correlated with six immune cell types (not only dendritic cells, but also B cells, CD4 + T cells, CD8 + T cells, neutrophils, and macrophages) in specific cancers, namely — THYM, THCA, and LIHC (except for neutrophils in THYM)." (PMID 37173675, 2023). "However, comprehensive research on CEP55 is lacking in pan-cancer." (PMID 37173675, 2023). "On the one hand, CEP55 may participate in the negative immune repose in certain cancers (e.g., STAD, and SKCM), since it shows an adverse relationship with the immune microenvironment in these cancers." (PMID 37173675, 2023).
tumor (91 papers, 2009 to 2026). "The analysis demonstrated that CEP55 expression levels were significantly higher in tumor tissues with various gene mutations than in normal tissues." (PMID 40918457, 2025). "Significantly, earlier functional genomic screening protocols identified CEP55 among 182 genes whose modification influenced tumor susceptibility to T cell‐mediated cytotoxicity." (PMID 40236779, 2025). "Given that tumors often arise from abnormal differentiation resulting from genomic chromosomal instability during cell division, significant upregulation of CEP55 is associated with tumor progression, invasion, and reduced survival." (PMID 40723362, 2025). "Studies have suggested that CEP55 is associated with adverse outcomes across various tumor types, potentially through its regulation of the cell cycle or by affecting exosomes." (PMID 40918457, 2025). "Loss of tapasin disrupts antigen processing, leading to impaired recognition by CTLs specific for tumour‐associated antigens such as survivin and CEP55, ultimately facilitating immune evasion and tumour progression." (PMID 40673641, 2025). "In our literature review, we found that genes such as SRSF3, TCF7L2, FOXP1, and CEP55 have been documented to be associated with epithelial-mesenchymal transition (EMT) in tumor cells." (PMID 38254188, 2024). "The tumor becomes more invasive and aggressive with each new mutation, and the CEP55 expression undergoes significant upregulation during tumor progression." (PMID 38250876, 2024). "Mechanically, the tumor suppressor effect of CEP55 knockdown is associated with dysregulation of the AKT and ERK signaling networks." (PMID 37274251, 2023). "Our findings also revealed a strong association between CEP55 levels and immune-related genes in most tumor types." (PMID 37887301, 2023). "This association offers an alternative mechanism for CEP55 to participate in the later stages of tumor progression and metastasis." (PMID 37484531, 2023). "Subsequently, using data from TCGA LIHC cohort and the GSE14520 dataset, we examined the association of tumor-associated clinicopathological characteristics with CEP55 expression." (PMID 37484531, 2023). "The elevated CEP55 expression in tumor tissue and its association with poor survival in HCC identified in this study corroborate previously published results." (PMID 37484531, 2023). "Collectively, our data demonstrates causative effects of deregulated Cep55 on genome stability and tumorigenesis which have potential implications for tumour initiation and therapy development." (PMID 33087841, 2020). "Taken together, these data highlight the crucial role of Cep55 in regulating proliferation and survival-associated signaling networks and its essential function in tumor formation." (PMID 33087841, 2020). "Recent studies have found that elevated expression of CEP55 is significantly associated with tumor stage, invasiveness, metastasis, and poor prognosis in multiple tumor types." (PMID 30096813, 2018). "Furthermore, loss of CEP55 in tumors dramatically rescued the immune suppressive tumor environment by reducing the tumor suppressive regulatory T cells and TCF1 markers." (PMID 38250876, 2024). "Notably, CEP55 expression increased with each new mutation in organoid-derived tumor tissues, with the basal level expression in shApc-derived polyps, followed by AKP tumors, and the highest in AKPS tumors." (PMID 38250876, 2024).
tumor (continued). "Similarly, we searched through the cMap tool for a large number of potential compounds associated with CEP55 expression in 9 different tumor cells and showed the top 50 promising compounds." (PMID 37887301, 2023). "Moreover, upregulation of CEP55 protein expression was significantly associated with ascites see tumor cells, which is one of the indications for accepting neoadjuvant chemotherapy." (PMID 26615423, 2016). "In light of these findings, our results suggest that overexpression of CEP55 protein is associated with tumor aggressiveness and may represent an independent prognostic factor for clinical outcomes in EOC patients." (PMID 26615423, 2016). "Notably, increased CEP55 expression in tumor samples was associated with LUAD prognosis." (PMID 39023191, 2024). "Additionally, higher mRNA levels of CDK1 and CEP55 were associated with tumor grade." (PMID 32587798, 2020). "In vivo trials illustrated that CEP55 knockdown inhibited tumor growth and downregulated key proteins in the TPX2-AURKA-PI3K-AKT and ferroptosis resistance pathway." (PMID 41617029, 2026). "To assess the effects of CEP55 knockdown on tumor growth and survival, we employed a mouse subcutaneous tumor model using 3LL cells (n = 5 per group)." (PMID 40236779, 2025). "Meanwhile, the expression level of CEP55 was also significantly correlated with the tumor TNM stage." (PMID 40918457, 2025). "Analysis of immune cell infiltration within the tumor microenvironment revealed a positive correlation between CEP55 expression and infiltration levels of B cells, CD8+ T cells, neutrophils, and dendritic cells." (PMID 40918457, 2025). "Colony formation assays demonstrated a significant reduction in the ability of tumor cells to form colonies following CEP55 knockdown (p < 0.05)." (PMID 40236779, 2025). "In both groups with reduced CEP55 expression (A2058 shCEP55-1 and A2058 shCEP55-2), tumor volume and weight were significantly lower than those in the NC group." (PMID 40918457, 2025). "The researchers primed the CTLs to respond to endogenous tumor-associated antigens (TAA), survivin, or cep55, and each Tsn-proficient WT." (PMID 40098955, 2025). "To validate our finding on the prognostic value of FBXO39 and CEP55 gene expression, we prepared RNA from our tumor samples of 29 patients." (PMID 40504854, 2025). "In this study, we identified a significant increase in FBXO39 and CEP55 expression in GBM tumor tissues compared to normal brains by wet bench as well as by bioinformatic pubic data analyses." (PMID 40504854, 2025). "In recent years, studies have found that CEP55 is abnormally overexpressed in various tumors and promotes tumor occurrence and development through mechanisms such as regulating cell proliferation, apoptosis, and metabolic reprogramming." (PMID 40918457, 2025). "The results showed that IGF2BP2, PLAU, and CEP55 were found to be statistically significantly higher expressed in tumours than in normal samples, while CMYA5 was statistically significantly lower expressed in tumours." (PMID 40762677, 2025). "Evidence indicates that CEP55 changes in tumor patients mostly consist of non-synonymous modifications, such as mutations, amplified values, and deep deletions." (PMID 40723362, 2025). "In this model, CEP55 knockdown resulted in reduced tumor weight and volume compared to the control group." (PMID 40236779, 2025). "By evaluating the differences in 24 types of immune cells between high and low CEP55 expression groups, it was found that CEP55 significantly inhibits tumor immune infiltration." (PMID 40386043, 2025). "Our study validated CEP55 overexpression in AM tumor tissues, revealing a relationship between CEP55 expression in tumor thickness and advanced TNM stage." (PMID 40918457, 2025). "Aberrant expression of CEP55 has relevance to the tumor microenvironment and immune regulation in BC." (PMID 39871389, 2025).
tumor (continued). "The results showed that APOC1, CEP55, hsa-miR-378a, hsa-miR-145, and hsa-miR-504 were significantly differentially expressed in tumor tissues compared to normal tissues." (PMID 38172247, 2024). "Tumor size, surgery type, ALP level, and 4 SE-associated genes (excluding CEP55 and DNAJB12) were significant prognostic factors for LMFS (all, P < 0.05)." (PMID 38254188, 2024). "In this study, we investigated the role of centrosomal protein 55 (CEP55) in shaping the tumor immune microenvironment in CRC." (PMID 38250876, 2024). "To further probe the role of CEP55 in tumorigenesis, we used tumor organoids as preclinical CRC models." (PMID 38250876, 2024). "More importantly, anti-PD1 treated WT showed a tumor size similar to isotype-control treated CEP55 KO tumor." (PMID 38250876, 2024). "Within the scope of this study, we also looked at CEP55 expression in tumor-secreted extracellular vesicles (TEVs), which are critical for intercellular communications between tumor cells and immune cells." (PMID 38250876, 2024). "Tumor immune infiltration analysis showed that APOC1 and CEP55 expression is associated with immune regulatory pathways and the function of multiple infiltrating immune cells." (PMID 38172247, 2024). "The subcutaneous tumor model showed that CEP55 knockout improves tumor T cell infiltration and restores an immune-active microenvironment." (PMID 38250876, 2024). "Future studies entail increasing the sample size, monitoring the tumor growth for extended periods, and examining the mechanism of anti-tumor response in the CEP55 KO tumors." (PMID 38250876, 2024). "More importantly, there was an inverse relationship between CEP55 expression and immune cell infiltration, particularly tumor T cell infiltration." (PMID 38250876, 2024). "LINC01087 knockdown reduced LINC01087 and CEP55 expressions and increased miR‐514a‐3p expression in tumor tissues." (PMID 39023191, 2024). "CEP55 knockout significantly impaired tumor growth in vitro and in vivo, suggesting that CEP55 plays a crucial role in tumorigenesis." (PMID 38250876, 2024). "Initially, the role of CEP55 was described only in the mechanism of cytokinesis, but recent studies have suggested its involvement in tumor progression." (PMID 38250876, 2024). "To investigate how the expression of CEP55 changes with tumor progression, we used CRC organoids harboring different combinations of CRC driver gene mutations." (PMID 38250876, 2024). "Immunofluorescence analysis was conducted on orthotopic tumor tissues from CEP55 knockout and CT26 wild-type (WT) tumors." (PMID 38250876, 2024). "The protein is expressed in normal tissues and tumor cells, and CEP55 can be coupled with the centrosome and intermediates in the cell cycle." (PMID 38696317, 2024). "Through CRISPR-Cas9 gene editing and preclinical CRC models, we demonstrated that CEP55 knockout leads to slower tumor growth, diminished immune suppressive markers, and a potential enhancement in responsiveness to anti-PD1 treatment." (PMID 38250876, 2024). "Our results suggested that the treatment of CEP55 knockout tumors with anti-PD1 leads to a reduction in tumor growth and size, suggesting the potential for improved efficacy by inhibiting CEP55." (PMID 38250876, 2024). "We identified CEP55 as a tumor cell-intrinsic factor important in mediating a tumor-suppressive microenvironment to promote T cell exclusion." (PMID 38250876, 2024). "We further explored the relationships between the expression of CEP55 and the abundance of tumor-infiltrating immune cells." (PMID 37484531, 2023). "To better characterize the mechanistic relationship between CEP55 and the tumor immunological milieu, we assessed the correlation between CEP55 expression and a collection of immunomodulators." (PMID 37484531, 2023).
tumor (continued). "As a next step, we investigated the correlation between CEP55 overexpression in tumor tissue and tumor grade and stage." (PMID 37175004, 2023). "Some studies have also reported that a high expression of CEP55 promotes tumor development, metastasis, and aggression by activating the PI3K/AKT signal pathway." (PMID 37173675, 2023). "We also found that increasing the methylation level of CEP55 significantly improved the prognosis of some tumor patients by epigenetic analysis." (PMID 37887301, 2023). "Defects in cytokinesis can cause the generation of aneuploid cells, which is a key step in tumorigenesis; therefore, CEP55 is suggested to be involved in tumor initiation." (PMID 37484531, 2023). "CEP55 is an oncoprotein that demonstrated upregulation in cancerous tissues in multiple human tumors, and this upregulation was positively correlated with tumor stage, grade, metastasis, and poor clinical outcomes." (PMID 37175004, 2023). "The knockdown of CEP55 can not only restrict the viability and proliferation of tumor cells but also induce their apoptosis." (PMID 37175004, 2023). "In the TUNEL assay, there were more TUNEL-positive cells were observed in the CEP55 knockdown tumor." (PMID 37274251, 2023). "As a result, it was important, after confirming the upregulation status of CEP55 in cancerous tissues, to ask for the consequences of this upregulation on tumor stage, grade, and metastasis." (PMID 37175004, 2023). "The relationship between CEP55 and the composition of tumor-infiltrating immune cells (TIICs) was first obtained by the TIMER2 and CIBERSORT algorithms." (PMID 37887301, 2023). "Our results showed that CEP55 expression was positively correlated with tumor purity in most tumors." (PMID 37887301, 2023). "We examined the effect of CEP55 on tumor prognosis using Kaplan-Meier (KM) and univariate Cox regression analyses." (PMID 37484531, 2023). "The variance of CEP55 expression levels among tumor and control groups was evaluated by the Wilcoxon rank-sum test and standardized mean difference (SMD)." (PMID 37173675, 2023). "The current study aimed to disclose the complete expression of CEP55, its effect on various malignancy prognoses, and its role in the tumor microenvironment." (PMID 37484531, 2023). "The expression of CDK1, MKI67, TOP2A, and CEP55 was significantly higher in tumor tissue than in normal tissue." (PMID 38134110, 2023). "Macrophage-derived exosomal miR-342-3p binds to neural precursor cell expressed, developmentally down-regulated gene 4-like (NEDD4L), and consequently elevates centrosomal protein 55 (CEP55) expression, thereby exerting tumor-promoting effects." (PMID 37834126, 2023). "CEP55 can affect the PI3K/AKT pathway and cell cycle, and the knockdown of CEP55 can inhibit tumor cell viability and proliferation and can even lead to tumor cell death." (PMID 37173675, 2023). "Next, to explore the differences in CEP55 between tumor tissues and corresponding paraneoplastic tissues, we analyzed CEP55 expression in different tumors in the TCGA dataset using the TIMER2 tool." (PMID 37887301, 2023). "The output from the TISDIB server revealed that KIRC, LGG, LIHC, UCEC (p < 0.001), HNSC, OV, and PAAD (p < 0.01) experienced a positive correlation between CEP55 expression and tumor grade." (PMID 37175004, 2023). "Increasing evidence suggests that activation of the AKT and ERK pathways plays an important role in CEP55’s promotion of tumor progression." (PMID 37274251, 2023). "CEP55, a member of the centrosomal protein family, has been shown to be highly expressed in many human tumor tissues and correlates with tumor malignancy, invasiveness, and poor prognosis." (PMID 37887301, 2023). "Since CEP55 is a well-studied oncogene, this 5′-isomiR of hsa-miR-101-3p acted as a potential tumor suppressor, which agrees with the tumor suppressor role of the canonical hsa-miR-101-3p form." (PMID 36275459, 2022).